IL6 (interleukin 6)
Diseases named in the same sentence as IL6 in open-access papers (continued):
Sharing a sentence is not in itself a finding about the gene and the disease.
colon carcinoma (continued). "For instance, it has been shown to interact with the transcription factor c-Fos in colon tumor cells, promoting the expression of vascular endothelial growth factor (VEGF) and IL-6, which in turn enhances the proliferation and migration of colon cancer cells." (PMID 40767963, 2025). "The PPI network, visualized through the STRING database, identified key targets such as AKT1, IL6, and HSP90AA1, which are implicated in colon cancer development." (PMID 41011246, 2025). "Numerous studies have found that Fusobacterium nucleatum is frequently enriched in colon cancer tissues, especially in the right colon, where it promotes production of proinflammatory cytokines like IL-6 and TNF-α." (PMID 41008758, 2025). "Secretion of IL-6 by highly metastatic colon cancer cells induces Kupffer cells to polarize to the M2 type, and KCs M2 polarization is essential for promoting the metastatic ability of colon cancer cells." (PMID 40034694, 2025). "Toadflax (BU) regulates KCs M2-type polarization and inhibits colon cancer liver metastasis through the SRC-3/IL-6 pathway." (PMID 40034694, 2025). "In colon carcinoma, IL-6 is expressed by MDSCs in the tumor microenvironment and tumor promotion is abrogated upon ablation of IL-6 expression and enhanced by IL-6 overexpression." (PMID 39338937, 2024). "One such cytokine is IL-6, deemed as a key cachectic factor in mice inoculated with colon carcinoma 26 (C26) cells, a widely used cancer cachexia model." (PMID 38671295, 2024). "IL-6 can stimulate colon cancer and activate the NF-κB pathway, as well as regulate intestinal tight junction, induce intestinal immunity, and incite intestinal inflammation." (PMID 39444683, 2024). "For example, in the mouse colon tumor model, both IL‐6 and parathyroid hormone‐related proteins, which are upregulated by COX‐2, were implicated in the onset of cachexia." (PMID 38807976, 2024). "Interleukin-6 is one of the key mediators of both acute and chronic inflammation and its elevated levels in the serum and tumor tissue of colon cancer patients have been reported." (PMID 39199686, 2024). "Subsequently, IL-6 affects the response of T cells, leading to immune escape of colon cancer and tumor progression." (PMID 39654892, 2024). "This study demonstrated that BZA directly binds to gp130, inhibiting IL-6 and IL-11 responses in several human colon cancer cell lines, xenograft, and patient-derived organoid models." (PMID 38600086, 2024). "Therapeutic doses of the betanin/capecitabine combination significantly downregulated the mRNA expression of the parameters TNF-α, NFκB, IL-1β, IL-6, and cyclin D1 compared to the colon cancer control." (PMID 38645563, 2024). "This study has also highlighted the need for investigation of IL6/IL6R-targeted therapies as novel treatment strategies for patients with colon cancer." (PMID 39766336, 2024). "where they demonstrated a downregulation of MUC2 production by colon cancer cells due to rIL-6 or macrophage-derived IL-6 treatment in a STAT3-dependent manner." (PMID 39170608, 2024). "In colon cancer, high levels of IL6 at the bulk mRNA level have been observed to predict increased risk of relapse." (PMID 39766336, 2024). "HFD demonstrated higher IL-6 and TNFα expression in colonic tumors than ND; HFD, ND + Ex, and HFD + Ex showed higher GPR109A expression in colon tumors than ND." (PMID 38792787, 2024). "SK has been found to inactivate the IL-6/signal transducer and activator of transcription 3 signaling and decrease A disintegrin and metalloproteinase 17 expression to suppress growth of colon cancer cells." (PMID 38745186, 2024).
colon carcinoma (continued). "IL6/GP130/STAT3 signaling promotes malignancy in colon cancer, while in gastric cancer, tumor mesenchymal stromal cells release IL-6 to promote EMT in cancer cells, further spreading the disease." (PMID 38519574, 2024). "CT26 and LoVo colon cancer cells were treated with 25 ng/ml IL-6 for different durations (0.5 and 24 h)." (PMID 38504172, 2024). "This study utilized the HT-29 colon cancer cell line to explore MAPK signaling’s role in IL-1β-induced IL-6 expression." (PMID 38671854, 2024). "Recent evidence suggests that TAMs enhance the invasion and metastasis of colon cancer cells by secreting interleukin-6 (IL-6) to induce EMT." (PMID 39594816, 2024). "We have previously shown that BZA interferes with IL-6 and IL-11 signalling to suppress tumour growth in preclinical models of gastric and colon cancer." (PMID 38600086, 2024). "A significant correlation was found between the titer of the autoantibodies and the IL-6 serum concentration in these colon cancer patients (p = 0.031)." (PMID 39518029, 2024). "Gene expression of GABRB3, GABRG2, and GAD1 positively correlated with genes involved in the synthesis of PGE2 (PTGS2 and PTGES) as well as IL‐6 in human colon cancer." (PMID 38886975, 2024). "Umesalma and Sudhandiran (2010), in nutritional experiments on rats with induced colon cancer, also observed that administration of ellagic acid downregulates IL-6 and that the effect is related to inhibition of NF-kappaB." (PMID 36678224, 2023). "Human liver CAFs from colon cancer metastases promote a malignant phenotype after the loss of expression of miR-10-5p present in normal liver fibroblasts, which suppresses proliferation, migration, and IL-6 and IL-8 levels in colon cancer cells." (PMID 37046676, 2023). "Resistin induces the activation of the Toll-like receptor 4 on the colon cancer cells and the overexpression of some growth factors, adhesion molecules, and proinflammatory cytokines (e.g., IL-6 and TNF-α) that promote tumor angiogenesis and metastasis." (PMID 37760840, 2023). "Overexpression of IL-6 has been well-studied in several malignancies including lung, breast, and colon cancer." (PMID 38075864, 2023). "High expression of TFRC promotes DSS-induced colonic epithelial cell death by activating the IL-6/IL-11-Stat3 pathway, which leads to mucosal injury and the occurrence of colon cancer." (PMID 37940859, 2023). "In this study, the serum levels of TNF-α and IL-6 in colon cancer patients were significantly different in different tumor lengths, depth of invasion and lymph node metastasis (all P < 0.001)." (PMID 37430251, 2023). "We and others have previously demonstrated that CAFs are major producers of tumor-promoting cytokine IL-6 at T2-3 stage tumor in colon cancer." (PMID 37185128, 2023). "Curcumin is an IL-6 inhibitor that has been previously used in a human gastric cancer xenograft model and mouse colon cancer model, demonstrating the inhibition of tumor growth, MDSCs in both blood and tumor tissue, and IL-6 levels." (PMID 36982282, 2023). "In colonic cancer patients, laparoscopic surgery conferred lower serum IL-6 and VEGF levels compared to open colectomy; however, local levels of the inflammatory and angiogenic cytokines were not significantly different between the two groups." (PMID 38067195, 2023). "In a prospective cohort study of 1,494 stage III colon cancer survivors, elevated hs-CRP and IL6 were associated with a 65% and 52% higher relative risk of disease recurrence or death, respectively." (PMID 38148846, 2023). "Regression analysis showed that serum levels of TNF-α, IL-6 and VEGF were independent risk factors for poor prognosis of colon cancer in elderly patients." (PMID 37430251, 2023). "Enhance the proliferation of CD3 T cells and IFN-γ T cells, significantly reduce the expression level of IL-6, and lead to immune escape of colon cancer." (PMID 38188683, 2023).
colon carcinoma (continued). "In this study, aspirin was shown to affect TCF/LEF, NF-κB, and NRF2 promoter transcriptional activities and downstream factors (c-Myc, IL-6, and HO-1) in human colon cancer cells." (PMID 38072949, 2023). "IL-6 triggers the phosphorylation of STAT3 in colon cancer cells, thereby facilitating their migration." (PMID 37981718, 2023). "Among them, IL-6 is one the most proinflammatory cytokines found in the TME, in both experimental and human colon cancer models, which has been associated with CRC progression and metastasis through activation of the STAT3 pathway axis in tumor cells." (PMID 37760840, 2023). "IL-6 has been demonstrated to promote tumor cell proliferation, cancer stem cells, and metastasis in colon cancer." (PMID 37185128, 2023). "STAT3 activity in colon carcinoma cells is triggered via interleukin-6 (IL6) or through a constitutively active STAT3 mutant promoted cancer cell multiplication." (PMID 35551547, 2022). "This leads to the transcription of proinflammatory cytokines IL‐6 and IL‐8, thereby stimulating migration and growth of human colon cancer cells." (PMID 34826187, 2022). "Activation of Janus kinase 2/signal transducer and activator of transcription (3 JAK2-STAT3) by other cytokines such as Interleukin 6 (IL-6) has also been reported in gastric carcinoma and colon cancer." (PMID 35875085, 2022). "Apple pectin, PC, also decreased the amounts of COX-2 and IL-6 in colon cancer cells HCT 116 pretreated with LPS." (PMID 35745651, 2022). "It has also been shown that miR-155-5p in M2 macrophages derived exosomes after transfer to colon cancer cells by targeting zinc-finger-type-containing 12B (ZC3H12B) leads to increased IL-6 expression, immune escape and tumor progression in colon cancer." (PMID 35550636, 2022). "As we previously showed in a murine colon cancer cachexia model, there was an induction of IL6 and Socs3 mRNA expression with a decrease in Lep mRNA expression in epididymal white adipose tissue." (PMID 35785158, 2022). "On the other hand, apple pectins were able to strongly reduce the level of COX-2 and IL-6 secreted by LPS-pretreated colon cancer cells, which pointed to their anti-inflammatory potency." (PMID 35745651, 2022). "Accordingly, macrophages have effect on colon tumor cells by IL-6 production and by activating STAT3 signaling pathway stimulate the production of IL-10." (PMID 35410210, 2022). "A study by Han and colleagues found that free fatty acids (FFA) were associated with serum levels of IL-6 and TNF-α in early stage and IL-6 levels in late-stage cachexia in gastric and colon cancer." (PMID 35328423, 2022). "To conclude, aerobic exercise‐conditioned serum reduced colon cancer cell proliferation in vitro, which appeared to be driven by IL‐6‐induced regulation of DNA damage and repair." (PMID 35213038, 2022). "The presence of IL‐6 in the conditioned media of human colon cancer‐derived mesenchymal stem cells enhances the migration and metastatic capability of CRC cells by upregulating Notch1 and CD44 levels." (PMID 35791509, 2022). "For instance, in colon cancer, TIMP-1-expressing CAFs are frequently present in those cancers associated with Crohn’s disease, a chronic inflammatory, IL-6-dependent disease." (PMID 36291767, 2022). "HCT-116 (Human Colon Cancer) cell lines were used to estimate the total antioxidant capacity and lipid peroxidation levels and pro-inflammatory markers (human IL-6, IL-1β, TNF-α)." (PMID 35204178, 2022). "In keeping with previous reports, TASCs promoted colon cancer cell proliferation through IL-6 secretion." (PMID 35454931, 2022). "PPARβ/δ deficiency in colon cancer cells reduces hypoxia-induced VEGF and IL6 expression, which links PPARβ/δ to tumor angiogenesis and immune response in colon cancer." (PMID 35954274, 2022).
colon carcinoma (continued). "Acute exercise also increased serum IL‐6, and stimulating colon cancer cells with recombinant IL‐6 reduced intracellular γ‐H2AX expression and cell proliferation in a dose‐dependent manner, mimicking the effect of exercise." (PMID 35213038, 2022). "To model the effect of inflammasome formation on adjacent colon cancer cells we first quantified the amount of IL-1β and IL-6 in the supernatant taken from the transfected and activated THP-1 cells by immunoblot." (PMID 35499706, 2022). "Among them, IL‐6 and IL‐8 have been known to promote the growth and migration of colon cancer cells." (PMID 34826187, 2022). "Chronic and/or overactivation of the inflammasome and resulting increase in IL-6 expression result in poor outcomes in colon cancer patients by activating STAT3." (PMID 35499706, 2022). "Its application resulted in the significant increase in COX-2 and IL-6 levels in all colon cancer cell lines tested." (PMID 35745651, 2022). "The tested derivatives revealed anti-IL-6 activity and significantly decreased the levels of the proinflammatory cytokine produced by both colon carcinoma cells." (PMID 34832881, 2021). "IL-6 promotes the survival of colon carcinoma cells in vitro; however blocking IL-6 signal prevents tumor growth 56-57." (PMID 33767595, 2021). "PEA reduces inflammation in human colonic tissue (from patients with IBD, colon cancer and appendicitis), including levels of IL-6, IL-8, IL-17A, MCP-1, and GM-CSF." (PMID 34916909, 2021). "Recent studies have shown that IL-6 modulates the immune status of the tumor microenvironment in a manner that facilitates the metastatic colonization of colon cancer cells through the alteration of antitumor effector cells." (PMID 33923292, 2021). "In particular, overproduction of IL-6 has been reported to trigger chronic intestinal inflammation and subsequently colon cancer." (PMID 33633749, 2021). "IL6, a multipotent proinflammatory cytokine, is known to be expressed in colon cancer tissues and plays a role in proliferation, metastasis and angiogenesis." (PMID 33911154, 2021). "FKBP14 promotes the proliferation and migration of colon cancer cells by targeting the IL-6/STAT3 signaling pathway." (PMID 34722557, 2021). "Higher tumoral expression of Foxp3, IL-17, IL1-beta, IL-6 and TGF-β was associated with the MSS phenotype, and the IL-17 T/TN (colon cancers/autologous normal colon mucosa) ratio was higher in MSS tissues than in MSI-H tissues." (PMID 35095898, 2021). "Studies have shown that ginsenoside rh2 upregulates the secretion levels of TNF-α and IL-6 in the serum of colon cancer mice, relieves tumor-related immunosuppression, and prolongs the survival of colon cancer mice." (PMID 33688358, 2021). "It has been reported that exosomal miR-155-5p derived from M2 macrophages can accelerate the occurrence and development of colon cancer via its effect on ZC3H12B-mediated IL-6 stability." (PMID 34445193, 2021). "The IL-6 produced in chronic inflammation has been shown to stimulate the CRP production in colon cancer cell lines." (PMID 34096454, 2021). "TAMs in colon cancer can secrete IL-1, IL-6, and TNF-α, and activate the nuclear factor NF-κB signaling pathway in the vascular endothelium to produce VEGF, which in turn promotes angiogenesis and alters the TME." (PMID 34445193, 2021). "UC can also cause tumorigenesis via the release of IL-6, IL-6 promotes the development of secondary tumors by increasing the invasiveness of colon cancer cells or promoting angiogenesis." (PMID 33841156, 2021). "In a mouse model of colon cancer, angiotensin II receptor blockers (ARBs) significantly reduced inhibitory T cells and a variety of immunosuppressive factors, including IL-6, IL-10, and VEGF." (PMID 34671200, 2021). "IL-6 is considered a growth factor for colon cancer cells; inhibition of IL-6 signaling slowed down the tumor cell’s growth." (PMID 35008550, 2021).
colon carcinoma (continued). "IL-6 was previously proposed as a preoperative serum marker for predicting colon cancer prognosis; it is also involved in promoting the stemness of colon cancer by provoking inflammation." (PMID 34120619, 2021). "The changes of these cytokines, especially IL-6, are consistent with the notion that IL-6 is critical for colon tumor development." (PMID 34702807, 2021). "The expression of GNAI2 in CD11c+ cells and IL6 in CD4+/CD11b+ DCs appears to promote colon tumor development in mice." (PMID 33828969, 2021). "Out of these, IL-6 is highly expressed in colon cancer cells and promotes progression into liver metastasis through IL-6/JAK/STAT signalling." (PMID 33669775, 2021). "Association between IL‐6/TNF‐α and the expression of LYPD8 in colonic tumor tissue, precancerous tissue and normal tissue at different stages." (PMID 33882644, 2021). "This can be induced by exposing colon cancer cells to IL6 or hydroxen peroxide in vitro and is thought to occur as a result of inflammation in sporadic and inflammatory bowel disease-associated cancers." (PMID 34298744, 2021). "Studies have found that adiponectin can inhibit the proliferation of colon cancer cells induced by interleukin-6 (IL-6) by inhibiting the activation and phosphorylation of STAT3 and thus has an anti-tumor effect." (PMID 34485124, 2021). "For instance, DC-derived IL-6 was found to promote colon cancer metastasis, drive TH17 differentiation in concert with IL-1 and TGF-β, and foster macrophage differentiation from monocytes." (PMID 33917526, 2021). "On the other hand, IL-6/8 secreted by TAMs facilitated the metastasis of colon cancer in a PTP4A3-KCNN4 dependent manner." (PMID 34630392, 2021). "The average number of colonic tumors and the levels of IL-6 and TNF-α in the CC + GL group were significantly lower than those in the CC group." (PMID 33807620, 2021). "Further, in colon cancer the release of cytokines as IL-1β, IL-6 and the activation of COX-2, collectively, support neoplastic transformation and malignant progression." (PMID 34679712, 2021). "Previous and our studies have shown a relationship between serum IL-6 levels and disease status in colon cancer patients." (PMID 33776564, 2021). "Our findings clearly show stimulation of IL-6 release from colon cancer cells by TRFi which indicates mutual IL-6 TRFi level regulation by tumor cells." (PMID 34681200, 2021). "Previous studies have reported that both MC38 and CT26 mouse colon cancer cells can up-regulate IL-6 expression." (PMID 34863141, 2021). "This study aims to exploit the anti-cancer properties of LPE using an in vitro system model of inflammation, consisting of IL-6-exposed human primary colon cancer cells." (PMID 34885656, 2021). "The activation of STAT3 by IL-6 in colon cancer was studied by examining HCT116 cells after IL-6 treatment, and specifically looking at STAT3 and pRKIP levels." (PMID 34944867, 2021). "In fact, elevated levels of IL-6 have been detected in the plasma of gastric and colon cancer patients and in gastric and colon cancer cell lines, confirming the role of IL-6 as a predictor of poor prognoses and as correlated to tumor aggressiveness." (PMID 34885656, 2021). "The level of serum interleukin-6, which has been shown to be an independent prognostic biomarker for survival in colon cancer, was lower after laparoscopic surgery." (PMID 33827601, 2021). "IL-1β induces expression of inflammatory cytokine genes IL-6 and IL-8 through CpG demethylation at the promoter sites of the IL-6 and IL-8 in human colon cancer epithelial Caco2 cells." (PMID 34220337, 2021). "Meanwhile, PTX-3 levels were positively correlated with the NF-κB and IL-6 levels in the breast and colon cancer." (PMID 33776564, 2021). "In a mouse experiment using the mouse colon cancer cell line CT-26, IL-6 deletion in mice enhances antitumor immunity by augmenting type-1 immunity, suggesting the immunosuppressive role of IL-6 in the tumor microenvironment." (PMID 33668122, 2021).